IL2 (interleukin 2)
Diseases named in the same sentence as IL2 in open-access papers (continued):
Sharing a sentence is not in itself a finding about the gene and the disease.
tumor (continued). "Next, ligand IL2 (a T cell differentiation signaling) binds to receptor IL2RC to trigger target gene JAM3, which could promote cell immune response and inhibit tumor cell growth." (PMID 31126066, 2019). "Both products exhibited a preferential accumulation at the tumor site, while IL2-KSF-TNFmut failed to localize to the neoplastic mass." (PMID 31799191, 2019). "Killing of αvβ6-positive pancreatic, breast or ovarian tumor cells and secretion of either IFN-γ or IL-2 was comparable after co-culture with A20-28z+ CAR T-cells, irrespective of whether they co-expressed an IL-8-responsive chemokine receptor or not." (PMID 31091832, 2019). "Interestingly, our data show that BALB/c mice have elevated counts of Tregs, which are able to be strongly activated and not so dependent on IL-2, data that could be related, at least in part, to the greater susceptibility to tumor development reported in this strain." (PMID 31824482, 2019). "However, large amounts can have pathologic effects, but the combined effects of IL-2 and adoptive cellular immunotherapy (ACI) showed to be the best options for the clearance of tumor." (PMID 31611927, 2019). "Comparing with Anti-IL-2 and EGFR inhibitor, a combination of castration with Anti-WNT5A or PLX yields better anti-tumor responses, indicating that blockade of the PC-Treg or PC-TAM interaction may effectively reduce tumor cell growth." (PMID 31504033, 2019). "The data implied that YFTL might exert anti-tumor effect by downregulating immunosuppressive molecules such as TGF-β1 and IL-10, and upregulating the level of IFN-Υ and IL-2." (PMID 30781674, 2019). "This indicates the presence of negative factors within the tumor, limiting the therapeutic effects of IL-2." (PMID 31462678, 2019). "Indeed other cytokines such as IL-2, IL-2, TNF-α, and IFN-γ are thought to regulate the metastatic tumor niche and play a key role in regulating cells of the immune system recruited into this environment." (PMID 31771091, 2019). "But as discussed, our CD8+ T cells were only incubated for less than a week in the presence of IL-2 and produced low levels of IFN-γ at the time of activation by the tumor, thus, it was highly unlikely that there was sufficient cytokine to promote PD-1 expression in such a short time frame." (PMID 31602007, 2019). "Meanwhile, tumor immune-related pathways were also enriched, such as B cell development pathway, cd28 signaling in T Helper cell, chemokine signaling, IL-1 signaling, IL15 signaling, IL-2 signaling, IL-3 signaling, IL-4 signaling, and IL-8 signaling." (PMID 31258820, 2019). "Therefore, we analyzed the levels of expression of IL-2, IL-2RA and CD27 together with CD40LG and the anti-apoptotic regulator BCL2L1 on CD8+ TILs isolated from peripheral blood and tumor tissues of Bhi OPSCC patients (n = 4; Cohort 3)." (PMID 31623665, 2019). "In addition, the upregulation of PDL1 expression decreased the expression of proinflammatory cytokines (IFN‐γ, IL‐2, and TNF‐α) in mouse serum and tumor tissue samples and increased the expression of anti‐inflammatory cytokines (IL‐10)." (PMID 31557409, 2019). "Furthermore, we injected the same molar of WT IL2-Fc and sumIL2-Fc into B16F10 tumor tissue to compare their respective TIL characteristics." (PMID 31462678, 2019). "Dual blockade of IL-2 and IL-15 abrogated the IL-1β enhancement of ACT-mediated tumor regression." (PMID 31405895, 2019). "Adoptive cell therapy using autologous tumor-infiltrating lymphocytes (TIL) has shown significant clinical benefit, but is limited by toxicities due to a requirement for post-infusion interleukin-2 (IL-2), for which high dose is standard." (PMID 30747243, 2019). "In addition to IL-2 and IFN-γ, RANTES is thought to induce the activation and proliferation of NK cells while enhancing the anti-tumor response in animal models." (PMID 31861351, 2019).
tumor (continued). "Mechanisms linking inflammatory cytokines and tumour growth and progression have not been established yet as some cytokines (IL2, IL11 and TGF beta) stimulate cancer breast growth and invasion, while others (IL12,IL 18and interferons) inhibit it." (PMID 31554361, 2019). "Clinical trials with combinations of antibodies to specific tumor antigens along with IL-2 treatment have not shown significant efficacy." (PMID 31114758, 2019). "Similarly, Dex derived from DCs loaded with lysates from chaperone-rich cells (CRCLs) and GL261 murine glioblastoma tumor cells induced proliferation and CTL activity of CD4+ and CD8+ T cells and enhanced the production of IL-2 and IFN-γ in vitro." (PMID 31615107, 2019). "We also confirmed that HSP70, a stress-inducible chaperone protein, was strongly expressed in the LP-iDOPE-treated NIR-exposed tumor tissues compared to the non-treated control or IL-2-producing tumor cells." (PMID 30719212, 2019). "Control cultures containing tumor fragments but without IL-2 or CD3/CD28 Dynabeads showed no expansion of TILs." (PMID 31398192, 2019). "Lipo-αCD137/Lipo-IL2-Fc combination therapy significantly delayed tumor outgrowth, while isotype control liposomes (Lipo-IgG) had no impact on tumor progression." (PMID 29295974, 2018). "By contrast, soluble anti-CD137/IL-2-Fc failed to elicit any anti-tumor effect, and all animals treated with the soluble combination died on day 10 due to accumulated in vivo toxicity." (PMID 29295974, 2018). "Results from such models show that sensitizing tumor cells with N-BPs, combined with adoptive transfer of ex vivo expanded human Vγ9Vδ2 T-cells with or without exogenous IL-2 administration is feasible and induces moderate anti-tumor responses." (PMID 29725332, 2018). "We found that IL-2-activated NK cells derived from co-cultures with tumor-derived MSC (NK/TAF) exerted lower cytotoxicity of Caco2, HCT15, and SW480 CRC cell lines, compared to NK cells cultured with IL-2 alone that were efficiently able to lyse CRC (NK/TAF vs NK in each panel)." (PMID 29910806, 2018). "Similarly, we have shown that IL-2/anti-CD40-activated macrophages can rescue age- and tumor-induced T cell function in vitro." (PMID 30459812, 2018). "Similarly, in tumor in B16-F10-bearing mice, SEP or αPD-L1 significantly increased IFN-γ and IL-2 levels compared with the control group (each treatment P < 0.05 for each cytokine, respectively, n = 6)." (PMID 29317734, 2018). "This was accompanied by reductions in tumor-associated CD8+ T cells expressing CD73 and IL-10 in elderly, but not young, IL-2/CD40-treated mice, relative to PBS controls." (PMID 30560130, 2018). "Furthermore, combination of tumor-antigen-targeting antibody, recombinant interleukin-2, anti-PD-1 and a powerful T cell vaccine has been recently shown to be extremely promising against B16F10-derived tumor." (PMID 29423067, 2018). "Although it is not an immunocytokine, it is important to analyze the effects of OMCP-mutIL-2, a mutated form of IL-2 (mutIL-2) linked to a high-affinity NKG2D ligand (OMCP), which is directed to cytotoxic immune effector cells rather than tumor cells." (PMID 30619269, 2018). "An IL-2 construct combining a glycosylphosphatidylinositol (GPI) anchor with a rigid peptide linker leads to functional IL-2 expression on the tumour cell surface and in the tumour microenvironment." (PMID 30410056, 2018). "NDV expressing both IL-2 and/or IL-12 was more efficient than NDV in stimulating INF-γ expression and inducing tumor regression in the murine hepatoma carcinoma model, resulting in immune memory against the same tumor rechallenge." (PMID 29857493, 2018). "In a first phase (elimination phase), the stimulated immune system produced many costimulating cytokines (TNFα, IL1, IFNα, TLR, ICAM1, IL2, IL12, IFNγ,) and less inhibitors (IL10, IL4, IL13, PD1/PD-L1, prostaglandins, LAG-3, TGFβ) resulting in efficient tumor cell killing." (PMID 29492219, 2018).
tumor (continued). "So, IL-2 or IL-15 increased the cytotoxic activity of NK cells but did not to increase the sensitivity of tumor cells to Avelumab-mediated ADCC." (PMID 30294328, 2018). "In the present study, we show that GD2.BBζ CAR-T cells could preferentially secrete high levels of Th1 cytokines, including IL-2, TNF-α, and IFN-γ, upon encountering a tumor cell and exert strong antitumor activity in vitro." (PMID 29298689, 2018). "It has been suggested that NK cells (cultured without/with IL-2/15) displayed enhanced cytotoxicity after a previous co-culture with certain tumor cells, although the exact priming stimulus was not identified." (PMID 30546366, 2018). "Depletion of macrophages using F4/80 antibody in elderly, but not young mice, improved IL-2/anti-CD40 immunotherapy up to 78% tumor regression." (PMID 30459812, 2018). "Analysis on a subpopulation of TILs in melanoma showed that tumor-reactive CD8+ T cells were largely derived from CD8+PD-1+ T cells, even though the level of PD-1 expression on CD8+ tumor-specific TILs decreased during culture with IL-2." (PMID 30409126, 2018). "meso-CART cells secreted high levels of interferon-γ (IFN-γ), interleukin-2 (IL-2), and tumor necrosis factor-α (TNF-α) in response to mesothelin+ tumor cells (Aspc-1-meso, Skov3-meso, Panc-1-meso, and Capan-2), but not mesothelin- cells (Aspc-1, Skov-3, and Panc-1)." (PMID 29568387, 2018). "The data above suggests elderly CD8+ T cells have reduced effector function and increased suppressive function, therefore we assessed the cytolytic capacity of young vs. elderly tumor-specific CD8+ T cells in TDLNs and tumors after two doses of IL-2/CD40 using an in vivo CTL assay." (PMID 30560130, 2018). "Conventional NK cell activation with IL-2 (1,000 UI/ml, 24 h) prior to the lysis assay showed a trend for an even further enhanced effect with tumor cells pretreated with selenite even though not statistically significant." (PMID 30324091, 2018). "In multiple tumor models, immunoliposome delivery achieves anti-tumor activity equivalent to free IL-2/anti-CD137 but with the complete absence of systemic toxicity." (PMID 29295974, 2018). "We have previously found that the administration of IL-2 has little to no anti-tumor effect on human CAR T cells activity in immunodeficient mice, if the CAR contains a costimulatory domain." (PMID 29980239, 2018). "Only the cytokines GM-CSF, IFN-γ, IL-2, IL-4 and TNF-α were detected at relevant concentrations in the presence of UniCAR CD28/ζ-armed T cells, tumor cells and TM substantiating that cytokine secretion occurs in a strictly TM- dependent- and target-specific manner." (PMID 29484126, 2018). "Taken together, this suggests that IL-2/CD40 alleviates suppressive CD11c+ cells in young, but not elderly tumors, likely contributing to reduced tumor responses to IL-2/CD40 by elderly mice." (PMID 30560130, 2018). "In contrast to the effect of TGFβ in combination with the K562 feeder cells, IL-2 plus TGFβ alone did not enhance the anti-tumor IFNγ and TNFα production, in agreement with what has been previously reported." (PMID 30400618, 2018). "We hypothesize that the addition of IL-2, anti-CTLA-4, or anti-PD-1/PD-L1 may reinforce CD8+ T cell function in the tumor microenvironment to further ameliorate antitumor efficacy of M-ILP." (PMID 30560089, 2018). "Importantly, increases in TNFα, IL-12p70 and IL-2 are not merely consequent of enhanced immune cell presence, as a number of other cytokines were unaltered by ibuprofen treatment including those associated with tumor associated macrophages, monocytes and M2 polarized macrophages [IL-4, IL-6, IL-10]." (PMID 30285905, 2018). "T-cell lines generated from PCa patients using the agonist peptide showed high levels of lysis of PAGE4-expressing tumor cells and enhanced secretion of Interferon gamma (IFN-g), granzyme B, Tumor Necrosis factor alpha (TNF-a), Interleukin 2 (IL-2) and lymphotactin." (PMID 29914187, 2018).
tumor (continued). "In contrast, IL-2/CD40 induced reduced MHC-I and CD80 in young, but not elderly, tumor-associated CD11c+ cells." (PMID 30560130, 2018). "Even after overcoming the hurdle of tumor infiltration, cell–cell contact between MDSCs and tumor-infiltrating lymphocytes inhibits effector-cell differentiation that is independent of activation status, IL-2 production or T-cell receptor signaling." (PMID 30619850, 2018). "In a syngeneic immunocompetent model, mice treated with murine meso.CAR-T had little tumor control but when combined with non-replicating Ad vectors expressing murine IL-2 and TNFa complete short-term tumor inhibition was achieved." (PMID 30298067, 2018). "These peculiar features of CD8+ T cells have been used to design unique IL-2 molecules and favor the expansion of cytotoxic anti-tumor rather than regulatory T lymphocytes." (PMID 30619269, 2018). "A pegylated IL-2, NKTR-214, which is a pro-drug and has the preferential release of the active IL-2 in the tumor microenvironment, has an excellent preclinical activity and is now being tested in combination with ICIs for multiple malignancies in multiple settings." (PMID 30577797, 2018). "These TCR sequences were detected in tumor tissue in addition to IL-2-expanded bulk TILs, but not among PBLs." (PMID 29545564, 2018). "Moreover, CXCR3 levels expressed on CD8+ T cells isolated from tumor-free WT and ADAM28 KO mice and stimulated ex-vivo with IL-2 and IL-7 were similar between both groups." (PMID 30647853, 2018). "Finally, when exogenously-administered to tumor-bearing MIF(-/-) animals, IL-2 restored the generation of Tregs and tumor growth." (PMID 29707160, 2018). "Among patients with recurrent stage 3 at the time of tumor tissue acquisition, 9/18 were still NED at the time of randomization; another who had developed M1c disease after resection had a complete response to interleukin-2-based biochemotherapy." (PMID 29510745, 2018). "Thus, IL2 can also activate CD4+CD25+Foxp3+ lymphocytes, which are capable of suppressing the T cell-mediated anti-tumor activity." (PMID 29467958, 2018). "Our results show the survival of G3-EGFRvIII CAR T-cells within the tumor as long as 90 days after a low-dose treatment and single administration without any need for ongoing IL-2 supplementation, accompanied by a marked tumor stroma demolition." (PMID 29975720, 2018). "Therefore, rather than simply suppressing T-regs function, in the context of the tumor microenvironment PI3K inhibitors enhance or sustain activation of weakly activated CD8 positive cytotoxic T-cells, possibly through IL2 signaling." (PMID 30587236, 2018). "For example, cytokines such as IL-2 and IFN-α are used to reduce tumor invasion in the skin." (PMID 29588627, 2018). "Systemic delivery of liposomal IL-2 and TNF-α have significantly reduced the tumor growth." (PMID 30424010, 2018). "Free αCD137/IL-2-Fc failed to control tumor growth and led to lethal immunotoxicity as before, but mice treated with Lipo-αCD137/IL-2-Fc showed no signs of toxicity and had a significantly lower tumor burden in the lungs than all other groups." (PMID 29295974, 2018). "Animal studies of dendritic cell (DC)-derived exosomes showed improved tumor microenvironment by a significant increase in CD8+ T lymphocytes, elevated levels of IFN-γ and interleukin-2, and decrease in CD25+Foxp3+ regulatory T (Treg) cells and of interleukin-10 and TGF-β in tumor sites." (PMID 30108680, 2018). "Our results suggest that the PE tumor microenvironment can shape NK cell polarization towards a low cytotoxic, decidual-like, highly proangiogenic phenotype and that IL-2 treatment is not sufficient to limit this process." (PMID 29713652, 2018). "Furthermore, combination of SEP and αPD-L1 significantly increase IFN-γ and IL-2 levels compared with SEP (each cytokine P < 0.05, respectively, n = 6) or αPD-L1 (each cytokine P < 0.05, respectively, n = 6) in tumor." (PMID 29317734, 2018).
tumor (continued). "BRAF inhibition also retained its therapeutic potential in BRAF-mutant tumours progressing on anti-PD-1 medication or on a sequential immunotherapy of high-dose interleukin-2 followed by ipilimumab with or without concurrent radiotherapy." (PMID 28571578, 2017). "These T cells were able to induce tumor regression as effectively as, if not better than, T cells grown in IL-2." (PMID 28146052, 2017). "Using regulatory T (Treg)-cell-enriched mouse tumor model, we determine that M6PRhigh IL-2 effectors but not M6PRlow IL-7 effectors adoptively transferred into tumors are vulnerable to Treg Gzm-B-mediated cell apoptosis." (PMID 28496990, 2017). "The concentrations of IL-2 and TNF-α also play an important role in the immune function, which may enhance the ability of tumor controlling for cancer patients." (PMID 29259647, 2017). "Pro-inflammatory cytokines such as IFN-γ, IFN-α and IL-2 as well as tumor-promoting factors like TGF-α were not detectable in our co-culture model." (PMID 28750018, 2017). "The IL-2 dependence prompted us to re-address the original experiment in NOG mice that did not result in tumor regression." (PMID 28955032, 2017). "We demonstrate that tumor-resident Treg cells preferentially eliminate M6PRhigh IL-2 effectors rather than M6PRlow IL-7-effectors through Treg Gzm-B-mediated cell apoptosis." (PMID 28496990, 2017). "Interestingly, there was a tumor x treatment interaction for the expression of both FGF-basic and IL-2 in the cortex." (PMID 27893434, 2017). "For example, in renal cell patients being treated with IL-2, pretreatment lymphocyte counts were predictive of improved overall survival independent of tumor response and patient characteristics." (PMID 28239396, 2017). "In this study, however, relatively low dose IL-2 (100 IU/ml) was used, some of the experiments used pure Vγ2Vδ2 T cells omitting accessory cells or used both IL-2 and IL-15, and the cells were not tested for their in vivo tumor activity." (PMID 28239463, 2017). "T cells released IFN-γ and IL-2 when co-cultured overnight with epitope-positive Raji and Daudi cells, but not with K562 or in the absence of a target tumor cell line." (PMID 29261129, 2017). "The adoptive transfer of murine splenic NK cells pretreated with IL-12, IL-15, and IL-18, but not naïve or IL-15- or IL-2-pretreated NK cells, into tumor-bearing mice effectively reduced tumor growth, than that of when combined with radiation therapy." (PMID 28955346, 2017). "The spleen cells were activated using the CD3/IL-2 method and stimulated with MCA205 tumor cells." (PMID 28854279, 2017). "Finally, based on tumor status, there were significant changes in proinflammatory cytokines (IFN-γ, IL-6, IL-5, IL-2, IL-10) and a growth factor (FGF-basic)." (PMID 27893434, 2017). "Given the requirement of the IL2 pathway for T cell activation and proliferation, NKTR-214 may serve as a backbone therapy that enhances multiple anti-tumor modalities." (PMID 28678791, 2017). "Treg-replete tumor-bearing mice were intratumorally injected with rapamycin-treated or non-treated IL-2 (CD45.1) effectors together with GranToxiLux, and 3 h later, mice were killed to collect tumors for analysis." (PMID 28496990, 2017). "In bortezomib-treated 4T1HA tumor-bearing mice, CD4+T-cells showed increased IL-2 production, CD11c+ dendritic cells showed increased IL-12 and IL-15 production, and HA-specific activated CD8+T-cells showed enhanced expression of IFNγ, granzyme-B and transcription factor eomesodermin." (PMID 28052005, 2017). "In contrast, M6PRhigh IL-2 effectors are preferentially killed by Treg Gzm-B-mediated lethal hit and failed to control tumor growth within the immunosuppressive tumor microenvironment." (PMID 28496990, 2017). "Survival was analyzed by tumor type related to timing of irAE and IL-2, and in those with or without exposure to CPI." (PMID 29254506, 2017).